HEY1 (hes related family bHLH transcription factor with YRPW motif 1)
Description:
Transcriptional repressor which binds preferentially to the canonical E box sequence 5'-CACGTG-3'. Downstream effector of Notch signaling required for cardiovascular development. Specifically required for the Notch-induced endocardial epithelial to mesenchymal transition, which is itself criticial for cardiac valve and septum development. May be required in conjunction with HEY2 to specify arterial cell fate or identity. Promotes maintenance of neuronal precursor cells and glial versus neuronal fate specification. Represses transcription by the cardiac transcriptional activators GATA4 and GATA6 and by the neuronal bHLH factors ASCL1/MASH1 and NEUROD4/MATH3. Involved in the regulation of liver cancer cells self-renewal.
Synonyms: CHF-2; bHLHb31; HESR-1; HRT-1; hHRT1; CHF2; HERP2; HESR1; NERP2; OAF1
Tractability: No criterion of Open Targets' tractability assessment is met for any kind of drug.
Gene: Protein-coding gene on chromosome 8 (79,762,371 to 79,767,857, reverse strand). Ensembl gene ENSG00000164683.
Subcellular location: Nucleus
Subcellular location (Human Protein Atlas): Nucleoplasm; Cytosol; Nuclear membrane
Pathways (Reactome):
Signal Transduction: NOTCH1 Intracellular Domain Regulates Transcription; NOTCH3 Intracellular Domain Regulates Transcription; NOTCH4 Intracellular Domain Regulates Transcription
Disease: Constitutive Signaling by NOTCH1 HD+PEST Domain Mutants; Constitutive Signaling by NOTCH1 PEST Domain Mutants
Developmental Biology: Cardiogenesis
Gene expression (Transcription): RUNX2 regulates osteoblast differentiation
Gene Ontology:
Molecular function: cis-regulatory region sequence-specific DNA binding; DNA-binding transcription factor activity; DNA-binding transcription factor activity, RNA polymerase II-specific; DNA-binding transcription repressor activity, RNA polymerase II-specific; protein binding; RNA polymerase II-specific DNA-binding transcription factor binding; sequence-specific double-stranded DNA binding; RNA polymerase II cis-regulatory region sequence-specific DNA binding; DNA binding; protein dimerization activity
Biological process: angiogenesis; negative regulation of DNA-templated transcription; negative regulation of Notch signaling pathway; negative regulation of smooth muscle cell differentiation; negative regulation of transcription by RNA polymerase II; Notch signaling pathway; anterior/posterior pattern specification; aortic valve morphogenesis; arterial endothelial cell differentiation; atrioventricular valve formation; cardiac conduction system development; cardiac epithelial to mesenchymal transition; cardiac septum morphogenesis; cardiac ventricle morphogenesis; circulatory system development; dorsal aorta morphogenesis; endocardial cushion morphogenesis; heart trabecula formation; labyrinthine layer blood vessel development; negative regulation of biomineral tissue development; negative regulation of neuron differentiation; positive regulation of transcription by RNA polymerase II; pulmonary valve morphogenesis; regulation of neurogenesis; regulation of vasculogenesis; and 4 more
Cellular component: nucleus; chromatin; cytoplasm; nucleoplasm
Genetic constraint (gnomAD): Loss-of-function variants: 9 observed, 25.15 expected, observed/expected ratio (o/e) 0.36, 90% interval 0.22 to 0.62. The upper end of that interval is the gene's LOEUF score, 0.62, which puts it in group 2 of 6, group 1 being the genes least tolerant of losing a copy. Missense variants: 385 observed, 403.06 expected, observed/expected ratio (o/e) 0.96, 90% interval 0.88 to 1.04. Synonymous variants: 213 observed, 179.69 expected, observed/expected ratio (o/e) 1.19, 90% interval 1.06 to 1.33.
Gene-disease validity (ClinGen):
ClinGen rates the evidence that HEY1 causes each of these diseases.
congenital heart disease (autosomal dominant): Disputed. A heart disease that is present at birth.
Cancer hallmarks: proliferative signalling (promotes); cell replicative immortality (promotes)
Homologues: Orthologues: chimpanzee HEY1 (100% identical), macaque HEY1 (99% identical), guinea pig HEY1 (98% identical), pig HEY1 (98% identical), rabbit HEY1 (96% identical), dog HEY1 (96% identical), rat Hey1 (95% identical), mouse Hey1 (95% identical), tropical clawed frog hey1 (83% identical), zebrafish hey1 (70% identical), Drosophila melanogaster cwo (17% identical), Drosophila melanogaster E(spl)mgamma-HLH (15% identical), and 7 more. Paralogues in human: HEY2 (57% identical), HEYL (47% identical), HELT (24% identical), BHLHE41 (22% identical), HES1 (22% identical), HES4 (21% identical), BHLHE40 (20% identical), HES6 (18% identical), HES7 (17% identical), HES2 (17% identical), HES5 (15% identical), HES3 (14% identical).
Diseases named in the same sentence as HEY1 in open-access papers:
HEY1 is named in the same sentence as 120 diseases in open-access papers, as found by Europe PMC text mining. Sharing a sentence is not in itself a finding about the gene and the disease. The quoted sentences say what the papers report.
breast carcinoma (30 papers, 2010 to 2025). "As Dlk1 mRNA levels were unaffected (not shown), we directly assessed the levels of active Notch and its downstream target Hey1 in mammary tumors derived from wild-type and Postn-deficient animals." (PMID 25592291, 2015). "Interestingly, deletion of Jagged1 promoted mouse mammary tumor formation from luminal cells but suppressed them from basal cells, associated with downregulation of Notch target genes Hey1 and Hey2, respectively." (PMID 39890784, 2025). "Interestingly, both HES1 and HEY1 have been implicated as part of the hypoxic response associated to breast cancer progression." (PMID 23826634, 2013). "CCL20-modulated PMN-MDSCs secreted amounts of CXCL2 and activated NOTCH1/HEY1 signaling pathway in breast cancer cells by binding to CXCR2, leading to the increase of ALDH+ BCSCs." (PMID 36859354, 2023). "Taken together, we confirmed that CXCL2-CXCR2 axis, which was activated by CCL20-modulated PMN-MDSCs, enhanced the stemness of breast cancer cells by NOTCH1/HEY1 signaling pathway." (PMID 36859354, 2023). "The results revealed that the expression of Hes1 and Hey1 was upregulated in colorectal and breast cancer cell lines." (PMID 37686467, 2023). "Hypoxia enhanced the expression of Notch target genes HES1 and HEY1 in different breast cancer cells." (PMID 36476410, 2022). "While previous studies have shown that both Hes1 and Hey1 are sensitive Notch target genes, Hey is more sensitive than Hes gene for Notch pathway inhibition in breast cancer." (PMID 25645291, 2015). "MRP1, Hes1 and Hey1 expression were all also increased after doxorubicin treatment in the MCF7 breast cancer cell line." (PMID 26362310, 2015). "Our data showed that the expression of the Notch signaling downstream genes Hes1 and Hey1 decreased in breast cancer cells with Notch1 inhibition." (PMID 25645291, 2015). "Hypoxia increased the expression of Notch target genes such as HES1 and HEY1 in breast cancer cells, as was expression of Notch receptors and ligands." (PMID 20010940, 2010). "Our study found that the expression of Notch target genes HES1 and HEY1 was increased in most breast cancer cells with hypoxia." (PMID 20010940, 2010). "Some studies have indicated that tumor-secreted CCL20 activates granulocyte–monocyte progenitor cell differentiation through its receptor CCR6, leading to the expansion of PMN-MDSCs, which activates the CXCR2/NOTCH1/HEY1 signaling pathway to increase ALDH+ breast cancer tumor stem cells." (PMID 40722739, 2025). "In addition, increased Notch4-Hey1 mRNA expression and decreased patient survival were found to be correlated in another study, confirming Hey1 as a marker for breast cancer development." (PMID 38007419, 2023). "This increase was more dramatic for HEY1 expression, suggesting that HEY1 may be a better marker of Notch activation in breast cancer cells." (PMID 36476410, 2022). "Furthermore, neural network-based deep learning models were established to predict breast cancer cell types using BCPRS-related genes (HEY1, IFNA13, NKX2-3, NR2F1, POU5F1, and YY1)." (PMID 34457116, 2021). "It is worth remarking that SOX6 and HEY1 are transcription factors associated with esophageal squamous cell carcinoma and breast cancer respectively, even though their roles in breast cancer and chemotherapy have not been thoroughly defined." (PMID 29540829, 2018). "HEY1 expression was at a very low level in these cancer cells under normoxia, and was greatly induced in these cells with hypoxia, indicating HEY1 gene is an excellent potential marker of Notch pathway activation in human breast cancer cell lines." (PMID 20010940, 2010). "In agreement with mouse experiments, high expression of JAG1 and HEY1 are associated with better overall survival among patients with luminal tumors, whereas high expression of JAG1 and HEY2 are both associated with worse overall survival in basal subtype of human breast cancer." (PMID 39890784, 2025).
breast carcinoma (continued). "However, the increased HEY1 expression by hypoxia was more dramatic compared with HES1 expression, indicating HEY1 might be a better marker of Notch activation in breast cancer cells." (PMID 20010940, 2010). "Our study utilized Western blot and RT-PCR assays to test the expression of Hes1 and Hey1 treatment with LAQ in colorectal and breast cancer cell lines." (PMID 37686467, 2023). "In summary, BCPRS and BCPRS-related genes (HEY1, IFNA13, NKX2-3, NR2F1, POU5F1, and YY1) can be used to evaluate the immune microenvironment and tumor purity in breast cancer patients." (PMID 34457116, 2021). "The low expression level of POU5F1 and YY1 and high expression level of HEY1, IFNA13, NKX2-3, and NR2F1 were significantly related to poor prognosis in breast cancer." (PMID 34457116, 2021). "Data suggests that deregulation of Notch signalling is an early event in breast cancer tumorigenesis, with accumulation of NICD and increased Hey1 expression detected in a broad range of subtypes, including ductal carcinoma in situ and epithelial hyperplasia." (PMID 34295896, 2021). "We also found that our deep-learning classifier predicted well (AUC > 0.65) on the CNA status in breast cancer, including six genes of FGFR1, EIF4EBP1, KAT6A, HEY1, ZNF217, and RAB25." (PMID 34556802, 2021). "Knockdown of ZEB1 in breast cancer cells inhibits Notch activity, including downregulation of JAG1, MAML2/3 and HEY1 expression, via de-repression of miRNA-200 expression." (PMID 34295896, 2021). "A multivariate Cox regression model was employed to establish a predictive model containing 6 characteristic genes (HEY1, IFNA13, NKX2-3, NR2F1, POU5F1, and YY1) correlated with the prognosis of breast cancer." (PMID 34457116, 2021). "Expression of the six BCPRS genes (IFNA13, HEY1, NKX2-3, NR2F1, POU5F1, and YY1) in breast cancer tissues was analyzed using Tabula Muris's FACS and droplet methods." (PMID 34457116, 2021). "p110 CUX1 overexpression in the breast carcinoma cell line Hs578T also increased the expression of ADAM17 and HEY1, a downstream target of NOTCH 50, whereas downregulation of p110 CUX1 in the same cells decreased the NOTCH signalling." (PMID 27941799, 2016). "Culture of other breast cancer cells under hypoxia also increased the expression of HES1 and HEY1 to different degrees, except for SK-BR-3 cells, which did not have an elevated HES1 expression under hypoxic conditions." (PMID 20010940, 2010). "Similarly, CXCL2 activated the Notch1/Hey1 signalling pathway in breast cancer cells, leading to an increase in ALDH+ breast cancer stem cells." (PMID 39523215, 2024). "Therefore, a neural network-based model was constructed to predict cell types in breast cancer tissues based on genes YY1, POU5F1, NKX2-3, NR2F1, HEY1, and IFNA13." (PMID 34457116, 2021). "MMPs, ADAMs, HES1/2, HEY1, c-Myc, CD44, EpCAM and Vimentin (downregulation of E-cadherin) engage in survival, stemness, EMT, invasion, ECM degradation/remodeling, angiogenesis, intravasation/extravasation, and metastatic colonization in breast cancer." (PMID 31694640, 2019). "In our study, we observed that HEY1 may be a target of miR-145, which showed decreased activity regardless of breast cancer subtype." (PMID 41463075, 2025). "The expression of Notch target genes such as HES1 and HEY1 were increased in MCF7 cells and MDA-468 cells when they were cultured at 1% O2 condition, indicating that hypoxia, presumably through induction of HIF factor expression, regulates Notch signaling in breast cancer cells." (PMID 20010940, 2010).
breast carcinoma (continued). "Interestingly, when we analysed existing clinical breast cancer cohort data, we found that the high expression level of HES5, but not HES1 or HEY1 was significantly correlated with a poor brain metastasis-free survival of breast cancer patients." (PMID 23495140, 2013).
glioblastoma (13 papers, 2014 to 2025). The most malignant astrocytic tumor (WHO grade IV). "In glioblastoma, for example, methylation of the oncogene, HEY1, was associated with increased DNA methyltransferase (DNMT) and decreased HDACi activities." (PMID 37432606, 2023). "For glioblastoma, POFUT1 knockdown reduces tumor volume and weight linked to decreased Notch activation (lower NICD, HES1, and HEY1 levels)." (PMID 40773107, 2025). "For instance, in glioblastoma stem cells (GSCs), HEY1 is upregulated by the STAT3/NF‐κB signaling pathway, which is constitutively activated in these cells." (PMID 38351531, 2024). "Hey1, a downstream effector of the Notch pathway, enhances the invasive and migratory capacities of glioblastoma by suppressing the transcription of the deubiquitinase USP11, which is associated with promyelocytic leukaemia (PML)." (PMID 38672496, 2024). "In the nucleus, acetyl-CoA is also a substrate that is used to methylate the Notch target gene HEY1 in glioblastoma as well as additional oncogenes in other tumor types." (PMID 37432606, 2023). "HEY1 (Hes-related family BHLH transcription factor with YRPW motif 1) is a transcription factor found upregulated in glioblastoma." (PMID 35954483, 2022). "In fact, HEY1 is a candidate oncogene that is highly expressed in glioblastoma 33, 34, rhabdomyosarcoma 35, hepatocellular carcinoma 36, head and neck squamous cell carcinoma 37, and renal cell carcinoma 38, among other cancers." (PMID 32284759, 2020). "In support of this, treatment with sodium butyrate (NaB), a histone deacetylase (HDAC) inhibitor, on 4910 and 5310 xenograft cell lines induced Glioblastoma cell apoptosis, decreased Hey1 expression, and increased DNMT1 levels." (PMID 30832246, 2019). "They found low levels of methylation on CpG islands within the HEY1 promoter across Glioblastoma specimens when compared to a healthy brain, resulting in Hey1 overexpression." (PMID 30832246, 2019). "The overexpression of Hey1, which is associated with survival and tumor grade, might be due to the impairment of Notch and E2F signaling; it was demonstrated that its overexpression in NSCs triggers neurosphere formation and contributes to Glioblastoma proliferation." (PMID 30832246, 2019). "These three findings indicate that further investigation of HEY1 methylation is warranted as it relates to novel glioblastoma treatments." (PMID 28574840, 2017). "In addition, CMRP5high Glioblastoma has elevated Hey1 expression compared to CMRP5low Glioblastoma, suggesting CMRP5 as an indicator of poor survival." (PMID 30832246, 2019). "On the other hand Hey1 has been related to a subset of molecules directly associated with hypoxia in glioblastoma tumors; and might be used as a marker to distinguish glioblastoma patients with a relative good prognosis (negative Hey1 expression)." (PMID 27669421, 2016). "Subsequently, we determined whether blocking of the Notch pathway could overcome the EFEMP1-mediated resistance to TMZ, by treating the Hs683-WT and Hs683-Rl glioblastoma cells that demonstrated high expression of HES1/HEY1 with TMZ and the γ-secretase inhibitor (GSI) DAPT." (PMID 24495907, 2014). "We previously reported that in glioblastomas, NOTCH1 pathway activation led to the upregulation of HEY1 and HEY2 transcription factors." (PMID 33925547, 2021). "In the current study, HEY1, a molecule that mediates Notch signaling, is found to be highly expressed in glioblastoma samples across multiple studies and appears to have a significant role in the proliferative and invasive abilities of GBM." (PMID 28574840, 2017). "Knockdown studies in colorectal, glioblastoma, and gastric cancer models have shown that reducing POFUT1 expression significantly decreases cleaved NICD levels, leading to lower expressions of HES1 and HEY1 and reduced tumor cell proliferation and invasion." (PMID 40773107, 2025).
glioblastoma (continued). "Moreover, combined treatment with DAPT represses HES1 and HEY1 expression, as well as LIF and YKL-40 levels, two new key players in Glioblastoma pathogenesis." (PMID 30832246, 2019). "In order to determine whether EFEMP1 overexpression resulted in the activation of the Notch signaling pathway in the TMZ-resistant glioblastoma cells, we first assessed the expression of the Notch-induced genes HES1 and HEY1 by qRT-PCR." (PMID 24495907, 2014). "N-acetylcysteine (NAC) inhibits glioblastoma cell proliferation, migration, and invasion and promotes Notch2 degradation, possibly through an Itch-dependent lysosomal pathway, while decreasing mRNA and protein levels of its downstream target genes, Hes1 and Hey1, thereby inducing apoptosis." (PMID 38672496, 2024). "Although PCR data does not show si-HEY1 to have a significant effect on STAT1, previous research indicates the overexpression of STAT1 is unique to glioblastoma samples when compared to normal brain tissue samples." (PMID 28574840, 2017).